JAK1 (Janus kinase 1)
Diseases named in the same sentence as JAK1 in open-access papers (continued):
Sharing a sentence is not in itself a finding about the gene and the disease.
vitiligo (25 papers, 2019 to 2025). Generalized well circumscribed patches of leukoderma that are generally distributed over symmetric body locations and is due to autoimmune destruction of melanocytes. "Tofacitinib, a JAK inhibitor that primarily targets JAK1/3, has been successfully used in the treatment of pediatric vitiligo by disrupting key signaling pathways involved in autoimmunity." (PMID 40656426, 2025). "Available data suggest that in the pathogenesis of vitiligo, the expression of JAK1 and JAK3 is upregulated, and key cytokines exert their effects via JAK receptors." (PMID 40136446, 2025). "More recently, topical JAK inhibitors, such as tofacitinib (JAK1/3 inhibitor) and ruxolitinib (JAK1/2 inhibitor), have been used with some success in vitiligo." (PMID 37985303, 2024). "Ifidancitinib is a JAK1/3 inhibitor that is currently under investigation in phase II clinical trials for the topical treatment of vitiligo." (PMID 39201060, 2024). "When conventional treatments are ineffective, patients with vitiligo can receive therapies such as JAK1/3 inhibitors or an IL-4 monoclonal antibody inhibitor to manage their condition." (PMID 38695020, 2024). "Both treatments are effective—indicating JAK1 is a key therapeutic target for vitiligo—but currently have black box warnings on their labels due to safety concerns associated with inhibiting multiple JAKs." (PMID 37925520, 2023). "JAK1 expression is higher in the lesional skin of vitiligo patients, and it correlates with a lower percentage of surviving melanocytes." (PMID 36902341, 2023). "It, along with Brepocitinib, a TYK2/JAK1 inhibitor, are currently being evaluated for their efficacy and safety profile in active vitiligo in combination with phototherapy." (PMID 36902341, 2023). "In a mouse model of vitiligo, local administration of the JAK1 siRNA significantly reduces skin infiltration of autoreactive CD8+ T cells and prevents epidermal depigmentation." (PMID 37925520, 2023). "Targeted treatment of vitiligo currently relies on the small molecule JAK1/2 inhibitor ruxolitinib (Opzelura) or off-label use of tofacitinib (a small molecule JAK1/3 inhibitor)." (PMID 37925520, 2023). "Another JAK1/3 inhibitor, tofacitinib citrate, induced a rapid and nearly complete repigmentation in a female patient with widespread and progressive vitiligo." (PMID 35096274, 2022). "Given that IFN-γ-JAK1/2-CXCL10 signaling in keratinocytes plays a major role in MSA-specific CD8+ T cell recruitment in vitiligo, the efficacy of a topical JAK1/2 inhibitor, ruxolitinib cream, was evaluated by a prospective randomized phase 2 trial." (PMID 35432377, 2022). "A case report described a rapid regression of vitiligo that occurred in a patient treated with a potent JAK1/2 inhibitor ruxolitinib, and the reduced CXCL10 levels were observed after the treatment." (PMID 35096274, 2022). "Targeting multiple cytokine pathways with JAK inhibitors is showing promising clinical outcome in vitiligo patients, as shown with the use of tofacitinib (blocking JAK1/3) or ruxolitinib (blocking JAK1/2)." (PMID 33936032, 2021). "Given that IFN-γ signaling is mediated through JAK1/2, baricitinib may be particularly effective in treating vitiligo." (PMID 40136446, 2025). "Moreover, in a case–control study, skin biopsies of 24 patients with active vitiligo and 20 healthy volunteers were analyzed to evaluate the expression of JAK1, 2, and 3 using RT-PCR." (PMID 38068541, 2023). "However, FHB therapy significantly hampered the increase of mRNA expression of Jak1, Jak2, Stat1, Stat2, and Stat3 in vitiligo mice, and this inhibitory effect was dose-dependent." (PMID 37575231, 2023). "In vitiligo, for example, IFN-γ produced by CD8+ T cells activates JAK1 and JAK2, leading to further recruitment of CD8+ T cells." (PMID 39161766, 2024). "IFN-γ-induced signature has been observed in human skin with vitiligo, with the upregulation of cytokines CXCL9 and CXCL10 via JAK1/2." (PMID 38975347, 2024).
vitiligo (continued). "To further investigate the effect of FHB on the JAK-STAT pathway in vitiligo mice at the transcriptional level, we used qRT-PCR to examine the influence of FHB on the mRNA expression of Jak1, Jak2, Stat1, Stat2, and Stat3 in the lesion region." (PMID 37575231, 2023). "JAK inhibitors (JAKi), such as tofacitinib (a pan JAKi) and ruxolitinib (selectivity for JAK1 and JAK2), have apparently reversed vitiligo in some case reports, and ongoing clinical trials." (PMID 37403086, 2023). "We demonstrate that, by harnessing a natural mechanism of gene silencing (RNAi), synthetic siRNA therapeutics can selectively silence JAK1 to inhibit IFN-γ-JAK1/2-STAT1-CXCL9/10/11 signaling and mitigate vitiligo pathogenesis." (PMID 37925520, 2023). "The JAK1/JAK3 inhibitor tofacitinib abrogates IL-4 signaling and the differentiation of Th2 cells; moreover, tofacitinib is an effective and well-tolerated therapy option for people with refractory vitiligo, according to numerous research." (PMID 38695020, 2024). "The JAK1/2 inhibitor ruxolitinib cream has been approved by FDA for treating non-segmental vitiligo patients over 12 years old." (PMID 38361944, 2024). "The patient was prescribed Opzelura (ruxolitinib) 1.5% topical cream, an inhibitor of the JAK1 and JAK2 proteins prevalent in the immune reaction responsible for vitiligo, as well as tacrolimus 0.1% topical ointment, another immunosuppressant, and was instructed to apply them over the affected area." (PMID 38817459, 2024). "Our developed siRNA potently silences human, non-human primate, mouse, and rat JAK1 mRNA expression, demonstrates therapeutic efficacy in a mouse model of vitiligo, and reduces the IFN-γ-dependent inflammatory response in human skin ex vivo." (PMID 37925520, 2023). "Interestingly, a phase 2 clinical trial evaluating the efficacy of systemic administration of a JAK1/TYK2 inhibitor is ongoing (NCT03715829) and will provide new insights into the physiopathology of vitiligo." (PMID 33936032, 2021). "JAK1 and JAK2 modulate the transduction signal after IFN-γ binds to its receptor, and as such, the downstream IFN-γ/CXCL10 signaling pathway may be a potential therapeutic target in vitiligo." (PMID 39201060, 2024). "Recent studies indicate that JAK1 and JAK3, but not JAK2, demonstrated higher cutaneous expression in vitiligo skin compared to healthy skin." (PMID 39201060, 2024). "Given the apparent critical role for IFNγ in driving vitiligo inflammation and its downstream signaling dependent on the JAK1-JAK2 heterodimer, it is perhaps not surprising that intense and diffuse JAK1 expression is more present within vitiliginous skin compared with healthy tissue." (PMID 31649667, 2019).
alopecia areata (24 papers, 2015 to 2026). Loss of scalp and body hair involving microscopically inflammatory patchy areas. "Our approach may therefore be particularly suitable for intralesional modulation of JAK1 for certain skin diseases, such as patchy hair loss in alopecia areata." (PMID 37925520, 2023). "By inhibiting JAK1/2, baricitinib disrupts this inflammatory cascade, reducing the autoimmune attack on hair follicles and potentially reversing alopecia areata." (PMID 40284470, 2025). "JAK3 was strongly expressed also in alopecia areata; JAK1 and JAK2 were to a lesser extent also elevated." (PMID 37624299, 2023). "Tofacitinib, ruxolitinib, baricitinib and upadacitinib are JAK1/2 inhibitors also used in alopecia areata." (PMID 34531850, 2021). "Ifidancitinib is another dual JAK1/3 inhibitor used for the treatment of alopecia areata." (PMID 36902341, 2023). "Baricitinib, a selective JAK1/JAK2 inhibitor, is the first targeted therapy approved by the FDA for systemic treatment of alopecia areata (AA)." (PMID 38903518, 2024). "tested biomarkers of scalp alopecia areata in patients who participated in the clinical trial, presenting that although brepocitinib can directly inhibit IFN-γ signaling through JAK1/2 activation, ritlecitinib can indirectly affect IFN-γ production through inhibition of TEC family kinases." (PMID 37138884, 2023). "For example, alopecia areata is driven by NKG2D+ CD8 T and is reversed by Jak1/3 inhibition." (PMID 37603573, 2023). "Further research is needed to better understand this rare presentation, including the possibility that inhibition of JAK1 alone may not be sufficient, potentially leading to drug-induced alopecia areata." (PMID 39258033, 2024). "This was confirmed by the rapid onset of anagen followed by hair growth in mouse and human skin after administering selective and reversible inhibitors of JAK1 and JAK2 an FDA-approved treatment option for the management of moderate-to-severe alopecia areata, autoimmune non-scarring alopecia." (PMID 40383754, 2025).
gastric cancer (21 papers, 2013 to 2026). A primary or metastatic malignant neoplasm involving the stomach. "The hyperactivation of JAK1 kinase has been closely associated with a wide range of human cancers, including liver, lung, breast, and gastric cancers 31,44-46." (PMID 39744421, 2025). "The gene has also been suggested to represent a biomarker and therapeutic target in gastric cancer to regulate cellular functions through JAK1/PI3K/AKT signaling." (PMID 41516419, 2026). "It has been reported that HOXA10 deteriorates gastric cancer through inducing Bcl-2 expression and activating JAK1/STAT3 signaling pathway." (PMID 36407869, 2022). "Significantly, increased TMB in JAK1 frameshift samples was also observed in prostate, colorectal, and gastric cancers (P < 0.001, all groups, Mann-Whitney U test)." (PMID 29121062, 2017). "Activated JAK1/STAT3 is crucial in gastric cancer proliferation and metastasis." (PMID 39136000, 2024). "Furthermore, CagA participates in cell signaling by activating the PIK3CA and KRAS pathways, ERK (MAPK), and MEK/ERK and JAK1 signaling pathway in gastric cancer cells." (PMID 23431236, 2013). "In addition, the ALKBH5 silencing disrupts gastric cancer tumorigenesis via the JAK1 axis." (PMID 39136000, 2024). "The JAK1 upregulation promoted the STAT3 phosphorylation and activated the JAK1/STAT3 pathway, which accelerated the progression of gastric cancer." (PMID 39136000, 2024). "ALKBH5 also removes the m6A modification of JAK1 mRNA, leading to upregulation of JAK1 expression mediated by LINC00659 in an m6A-YTHDF2-dependent manner, consequently activating the JAK1/STAT3 pathway in gastric cancer." (PMID 39136000, 2024). "MTMR2 promotes invasion and metastasis of gastric cancer via inactivating IFNγ/STAT1 signaling and modulates TIME by promoting the progression of NK/T cell lymphoma by targeting JAK1." (PMID 39408697, 2024). "The most specific loci were in the exons of genes JAK1 and CHD3 (for endometrial cancer); BMPR2, ELAV3, GLYR1, and ZNF43 (for colon cancer); and XYLT2 (for stomach cancer)." (PMID 37894432, 2023). "Including JAK1, JAK2, JAK3, and Tyk2, various JAKs are always activated by cytokines to mediate the gastric cancer cells progression, such as JAK1 kinase by IL-10 family cytokines, JAK2 kinase by G-CSF factor, Tyk2 kinase by cytokine IL-23, respectively." (PMID 35734442, 2022). "Of the three pathways that utilize JAK1, only IFN response was significantly down regulated in both endometrial and stomach cancers." (PMID 29121062, 2017). "In gastrointestinal cancers, JAK1 frameshifts were observed in 6% (9/158) and 15% (4/27) of MSI-H colorectal and gastric cancers, respectively." (PMID 29121062, 2017).
lupus (21 papers, 2020 to 2025). "Several JAK inhibitors have been investigated in systemic lupus erythematosus, including baricitinib (JAK1/2 inhibitor), tofacitinib (JAK1/3 inhibitor), and the selective TYK2 inhibitor deucravacitinib." (PMID 41373894, 2025). "Baricitinib is an oral selective inhibitor of Janus kinase 1/2 that has achieved clinically meaningful outcomes for systemic lupus erythematosus (SLE)." (PMID 40305472, 2025). "Baricitinib, a selective JAK1/2 inhibitor, significantly suppressed lupus-like symptoms and restored disrupted podocyte structures." (PMID 38022642, 2023). "Data from murine lupus models indicated a significant improvement in skin modifications in MRL/lpr mice treated with the selective JAK1/2 inhibitor ruxolitinib." (PMID 36233087, 2022). "Topical treatment with a JAK1-specific inhibitor significantly improves CLE-like skin lesions in a lupus-prone TREX1–/– -mouse model and appears to be a promising therapeutic approach for CLE patients." (PMID 32194562, 2020). "Moreover, in the MRL/lpr lupus model, the JAK1/JAK3 inhibitor tofacitinib ameliorated renal manifestations, while decreasing plasma anti-dsDNA levels and proteinuria." (PMID 41573545, 2025). "Finally, one patient (E1) with systemic lupus erythematosus who was clinically well controlled under mycophenolate mofetil but because of disabling digestive intolerance was switched to baricitinib (JAK1/2 inhibitor) at 2 mg once daily followed by 2 mg twice daily." (PMID 33087723, 2020). "Increased numbers of pDCs, together with their hyperactivation via stimulator of interferon genes (STING)/IFN-α/JAK1/STAT1 signaling, resulted in higher IFN-α levels and ISG expression, explaining the impact of NCF1-derived ROS on lupus severity." (PMID 36853827, 2023). "Ruxolitinib, a relatively specific inhibitor of JAK1 and JAK2, was administered to the MLR/lpr model to investigate its effect on lupus-related skin lesions." (PMID 37457579, 2023). "Having found that ROS-deficient pDCs displayed increased IFN-α production and type I IFN responses via the STING and JAK1/STAT1 pathways, we further investigated if these hyperreactive cells exacerbate lupus." (PMID 36853827, 2023). "Of importance, here we showed that hyperactivated IFN-α/JAK1/STAT1 signaling, in concert with increased STING-dependent IFN-α production in Ncf1m1j/m1j pDCs, acting as a positive feedback loop, augments type I IFN responses, which may be crucial to lupus exacerbation driven by ROS deficiency." (PMID 36853827, 2023). "A selective inhibitor for JAK1 and JAK2, approved for use in rheumatoid arthritis, recently demonstrated its potential as an agent for the treatment of lupus patients." (PMID 36015084, 2022). "Topical treatment with JAK1-specific INCB039110 for 7 days continuously improved skin lesions regarding erythema, induration, scaling and size leading to a strongly reduced lupus-skin-activity-score (adapted CLASI score) compared to placebo-treated mice." (PMID 32194562, 2020). "Collectively, the present study demonstrated that baricitinib, a selective inhibitor for JAK1 and JAK2, could mitigate autoimmune features in lupus-prone mice by suppressing eccentric B cell activation and recovering structural injuries of podocytes." (PMID 34497607, 2021). "Selective pharmacological JAK1 inhibition significantly reduces the expression of typical proinflammatory mediators such as CXCL chemokines, BLyS, TRAIL, and AIM2 in CLE in vitro models and also improves skin lesions in lupus-prone TREX1–/– -mice markedly." (PMID 32194562, 2020). "In preclinical lupus models, including MRL/lpr and NZB/W F1 mice, JAK inhibition has yielded beneficial effects: JAK2–STAT1 blockade reduced glomerular immune complex deposits, proteinuria, and inflammatory infiltrates; JAK1/STAT3 inhibition decreased disease severity and autoantibody levels." (PMID 41194923, 2025).
lupus (continued). "For instance, filgotinib and upadacitinib, both selective inhibitors of JAK1, are promising candidates in the future, as well as the monoclonal antibody to type I IFN receptor subunit 1 (IFNAR1) anifrolumab, which showed promising effects in systemic lupus erythematosus." (PMID 35418997, 2022). "JAK1 did not fit this pattern in the present study of lupus patients, suggesting that this pattern of gene expression may be specific to the disease state." (PMID 34847931, 2021).
lymphoma (21 papers, 2018 to 2026). A malignant (clonal) proliferation of B- lymphocytes or T- lymphocytes which involves the lymph nodes, bone marrow and/or extranodal sites. "Ruxolitinib, a JAK1/2 inhibitor, is effective in suppressing the proliferation of tumor cells and benefits the patients with this lymphoma." (PMID 35406421, 2022). "Inhibitors that are able to attenuate JAK1/STAT3 signalling have been shown to suppress cell proliferation of lymphoma and oesophageal cancer." (PMID 33523587, 2021). "In contrast to the upregulation of SHP-1, BTZ@HMSNs decreased the mRNA levels of c-Kit, NF-κB, and JAK1, which elicit oncogenic role in lymphoma development." (PMID 33290262, 2020). "An ongoing phase II trial is being conducted to explore the efficacy of the JAK1/2 inhibitor ruxolitinib in patients with R/R lymphoma, including PTCL (NCT01431209)." (PMID 32448357, 2020). "Recent studies have identified JAK1 as an oncogenic driver in various lymphomas, particularly in relapsed or refractory peripheral T-cell lymphoma (PTCL), where its sustained activation is associated with enhanced tumor proliferation, survival, migration, and suppression of anti-tumor immunity." (PMID 41438753, 2025). "GOF mutations in JAKs (JAK1, JAK2, JAK3) and STATs (particularly STAT3 and STAT5B), as well as alterations in cytokine receptors (IL7R, CRLF2) and negative regulators (SOCS1, PTPN2), are recurrent in myeloproliferative neoplasms and certain lymphoid cancers." (PMID 41438753, 2025). "In our results, some of the differentially methylated genes in EHMT2 + MCL cases have also been reported with recurrent genetic alterations in lymphoma, such as ALK, DUSP22, NCOR2, RORA, DLC1, JAG1/2, JAK1, NOTCH4, and CD1938–45." (PMID 34633777, 2021). "In advanced stages of a lymphoma, STAT3 and STAT5 are completely dependent on the constitutively activated JAK1 and JAK3." (PMID 34948183, 2021). "IL-15 is a proinflammatory cytokine that contributes STAT activation by mediating JAK1 and JAK3 phosphorylation, leading to lymphoma cell growth and survival." (PMID 34079795, 2021). "Golidocitinib, a selective JAK1 inhibitor, demonstrated substantial anti-tumor activity in r/r PTCL, which suggests potential utility in CTCL given the overlapping molecular features between these lymphomas." (PMID 40002165, 2025). "Recently, a study including two cohorts of 626 and 929 patients with MPN observed that patients treated with JAK1/2 inhibitors developed aggressive lymphomas (n = 6) 15–16-fold more frequently than patients not exposed to these treatments." (PMID 33092233, 2020). "Although JAK1/JAK2 inhibitors have been shown to inhibit growth of canine lymphoma cells and malignant mast cells in vitro, there is no published data regarding the effects of such JAK inhibitors on canine tumor cell lines derived from solid tumors." (PMID 31409327, 2019). "Despite resistance to multiple biologic disease-modifying anti-rheumatic drugs (bDMARDs), including adalimumab and tocilizumab, treatment with the Janus kinase 1/2 inhibitor ruxolitinib achieved clinical remission sustained for over two years without significant adverse events or lymphoma relapse." (PMID 41883911, 2026).